RN7SL265P (RNA, 7SL, cytoplasmic 265, pseudogene)
Gene: Miscellaneous RNA gene on chromosome 7 (73,732,569 to 73,732,868, reverse strand). Ensembl gene ENSG00000241709.
Homologues: Orthologues: chimpanzee Metazoa_SRP (93% identical), guinea pig Metazoa_SRP (58% identical). Paralogues in human: RN7SL1 (81% identical), RN7SL2 (80% identical), RN7SL3 (79% identical), RN7SL126P (78% identical), RN7SL45P (78% identical), RN7SL655P (78% identical), RN7SL711P (78% identical), RN7SL336P (77% identical), RN7SL679P (77% identical), RN7SL230P (77% identical), RN7SL296P (77% identical), RN7SL478P (77% identical), and 701 more.